TTC24 (tetratricopeptide repeat domain 24)
Tractability: No criterion of Open Targets' tractability assessment is met for any kind of drug.
Gene: Protein-coding gene on chromosome 1 (156,579,723 to 156,587,719, forward strand). Ensembl gene ENSG00000187862.
Subcellular location (Human Protein Atlas): Nucleoplasm
Gene Ontology:
Molecular function: protein binding
Genetic constraint (gnomAD): Loss-of-function variants: 53 observed, 61.16 expected, observed/expected ratio (o/e) 0.87, 90% interval 0.69 to 1.09. The upper end of that interval is the gene's LOEUF score, 1.09, which puts it in group 4 of 6, group 1 being the genes least tolerant of losing a copy. Missense variants: 679 observed, 718.89 expected, observed/expected ratio (o/e) 0.94, 90% interval 0.89 to 1.01. Synonymous variants: 276 observed, 299.08 expected, observed/expected ratio (o/e) 0.92, 90% interval 0.84 to 1.02.
Homologues: Orthologues: chimpanzee TTC24 (99% identical), macaque TTC24 (93% identical), pig TTC24 (77% identical), rabbit TTC24 (67% identical), tropical clawed frog ttc24 (36% identical), rat Ttc24 (35% identical). Paralogues in human: GPSM2 (19% identical), GPSM1 (19% identical), TTC28 (18% identical), TTC29 (8% identical), RAPSN (8% identical), GPSM3 (4% identical).